PRKCSH (PRKCSH beta subunit of glucosidase II)
Diseases named in the same sentence as PRKCSH in open-access papers (continued):
Sharing a sentence is not in itself a finding about the gene and the disease.
tumor (continued). "Therefore, we utilized the CPTAC database to compare and analyze the difference of PRKCSH protein expression between tumor and normal samples." (PMID 38245572, 2024). "Overall, our findings indicate that PRKCSH may represent a promising candidate for future tumor immunotherapy efforts." (PMID 38245572, 2024). "Elevated levels of PRKCSH correlated with the expression of tumor-promoting genes." (PMID 38571496, 2024). "Moreover, PRKCSH modulates anti-tumor immunity, with its suppression augmenting NK cell and T cell activity, promising enhanced cancer therapy." (PMID 38571496, 2024). "PRKCSH overexpression contributed to a reversal of the anti-tumor effect of circCOL5A1 silencing." (PMID 37660068, 2023). "Lastly, since we showed that the levels of PRKCSH mRNA were elevated in several tumor tissues, we checked whether the expression levels of XBP1 target genes were elevated in human tumors." (PMID 31320625, 2019). "However, when PRKCSH is knockout, it increases macrophage infiltration and shifts macrophage differentiation toward an M1-like phenotype, which boosts a pro-inflammatory anti-tumor immune response." (PMID 41350724, 2025). "In addition, examining other tumor types will help determine whether PRKCSH effects are context-dependent, and further studies are needed to delineate how PRKCSH regulates cytokine secretion, particularly IL-6 and IL-8." (PMID 41350724, 2025). "Therefore, PRKCSH might be an important factor in acquiring cross-resistance in tumor cells against TNFSF." (PMID 38200153, 2024). "It is clear that PRKCSH is critical for regulating the balance between the two caspase-8 modes of action, which may be involved in the regulation of NK cell-mediated antitumor immunity as well as tumor cell growth." (PMID 38200153, 2024). "Consequently, higher PRKCSH expression in tumor patients suggests an unfavorable prognosis." (PMID 38245572, 2024). "Thus, PRKCSH may be a critical target for overcoming tumor resistance against NK cell-mediated antitumor immunity as well as for combating TNFSF resistance." (PMID 38200153, 2024). "PRKCSH may function as an oncogene influencing tumor progression and prognosis." (PMID 38245572, 2024). "Finally, we investigated whether IRE1α is required for PRKCSH-mediated expression of tumor-promoting cytokines under ER stress." (PMID 31320625, 2019). "The expression of PRKCSH, IRE1α, and BIP is significantly higher in tumor (T) tissues than in normal (N) adjacent tissues." (PMID 41350724, 2025). "To examine the role of PRKCSH in TNFSF resistance, we determined the cytotoxicity of TNFSF when it was directly applied to PRKCSH-depleted tumor cells." (PMID 38200153, 2024). "Overall, the upregulation of PRKCSH in tumor tissues suggests a molecular rationale for altered IRE1α–XBP1 signaling in and adaption of tumor cells to ER stress." (PMID 31320625, 2019). "This notion is supported by our co-culture experiments and gene-expression analyses, which revealed that macrophages shifted toward a pro-inflammatory, anti-tumor phenotype when PRKCSH was absent." (PMID 41350724, 2025). "Mechanistically, PRKCSH interrupts TNFSF-mediated apoptotic signaling by promoting IGF1R activation in tumor cells without affecting the expression of TNFSF receptors, resulting in the inhibition of tumor cell death." (PMID 38200153, 2024). "Additionally, PRKCSH has been identified as a selective activator of the IRE1α branch of the unfolded protein response (UPR), contributing to tumor cell adaptation to stress and the initiation of tumorigenesis." (PMID 38571496, 2024). "Collectively, these results suggest an augmented immune response against cancer cells in the absence of PRKCSH, highlighting its potential as a therapeutic target for improving anti-tumor immunosurveillance." (PMID 38571496, 2024). "Furthermore, PRKCSH methylation displayed a significant negative correlation with its expression in 27 tumor types, with a marked decrease compared to normal tissues in ten tumors." (PMID 38245572, 2024).
cancer (8 papers, 2019 to 2025). A tumor composed of atypical neoplastic, often pleomorphic cells that invade other tissues. "Consistent with the results in PRKCSH-deficient cancer cells, overexpression of PRKCSH-WT or ΔG2B in H460 cells increased IGF1R protein levels." (PMID 38200153, 2024). "Key findings revealed that PRKCSH exhibited overexpression in most tumors, with a significant association with poor overall survival (OS) in six cancer types." (PMID 38245572, 2024). "According to the GSEA analysis, PRKCSH was implicated in diverse cancer-linked immune pathways, mainly including adaptive immune response, response to chemokine, cytokine and so on, which reinforced our belief in PRKCH's immune role in tumors." (PMID 38245572, 2024). "Our study identified genetic and epigenetic changes in PRKCSH as important mechanisms in carcinogenesis, with hypomethylation of PRKCSH associated with poor prognosis in some cancer types." (PMID 38245572, 2024). "Targeting PRKCSH and its associated pathways emerges as a potential therapeutic strategy for cancer management." (PMID 38571496, 2024). "We conducted single-cell function analysis using CancerSEA and found that PRKCSH was associated with various functional states of cancer cells." (PMID 38245572, 2024). "Subsequently, the potential role of PRKCSH in TNFSF resistance was confirmed by ectopic overexpression of PRKCSH-WT or ΔG2B in PRKCSH-deficient cancer cells." (PMID 38200153, 2024). "Then, we used PPI Network and GSEA analysis to explore the underlying mechanism of PRKCSH in tumorigenesis and cancer development." (PMID 38245572, 2024). "Emerging evidence indicates that PRKCSH is involved in tumorigenesis and associated with poor prognosis in specific types of cancer." (PMID 38245572, 2024). "Subsequently, we explored the potential association between PRKCSH alteration and survival outcomes in pan-cancer." (PMID 38245572, 2024). "When PRKCSH was reduced, cancer cells became more susceptible to TNFs and were more effectively eliminated by immune cells known as natural killer cells." (PMID 38200153, 2024). "Moreover, PRKCSH exhibited significant correlations with TMB in five cancer categories, MSI in eight, and displayed associations with immune cell populations in pan-cancer analysis." (PMID 38245572, 2024). "Dysregulation of PRKCSH has been linked to various diseases, including cancer." (PMID 38571496, 2024). "PRKCSH is upregulated in a variety of tumors and associated with cancer prognosis." (PMID 38245572, 2024). "In coping with these challenging conditions, it is hypothesized that the increased expression of PRKCSH assists in meeting the heightened demand for N-linked glycoproteins in cancer cells." (PMID 38571496, 2024). "IL-6 and IL-8 secretion was suppressed in PRKCSH-knockout (KO) cancer cells, disrupting cytokine-mediated immune suppression." (PMID 41350724, 2025). "Further investigations are needed to elucidate PRKCSH’s precise role and validate its therapeutic potential in cancer treatment." (PMID 38571496, 2024). "PRKCSH overexpression correlates with poorer prognosis in various cancers, implicating its role in initiating and promoting tumorigenesis." (PMID 38571496, 2024). "To comprehensively assess PRKCSH’s significance across cancers, we conducted a pan-cancer analysis using data from The Cancer Genome Atlas (TCGA), Genotype-Tissue Expression (GTEx), and Cancer Cell Line Encyclopedia (CCLE)." (PMID 38245572, 2024). "PRKCSH emerges as a dual player in cancer immunotherapy, serving as both a therapeutic target and a biomarker." (PMID 38571496, 2024). "In summary, the expression of PRKCSH was inversely correlated with its methylation level in 27 cancers, excluding ESCA, CHOL, COAD, GBM, LAML, and PCPG." (PMID 38245572, 2024). "The induction of PRKCSH in cancer and its interaction with various cellular components suggest broader roles beyond its previously known functions." (PMID 38571496, 2024).
cancer (continued). "This review highlights the intricate interplay between PRKCSH (GluIIβ) and cancer, emphasizing its significance in various cellular processes and its potential as a key player in cancer-related mechanisms." (PMID 38571496, 2024). "Downregulating PRKCSH expression or blocking the activity of glucosidase II has been documented to prompt cancer cell death through the initiation of both autophagy and apoptosis pathways." (PMID 38571496, 2024). "At present, we have performed a systematic analysis of PRKCSH across 33 cancers using multiple public databases." (PMID 38245572, 2024). "To elucidate the potential function of PRKCSH across different cancer types, we examined its mRNA expression levels in pan-cancer cohort." (PMID 38245572, 2024). "We then grouped cancer patients according to the expression level of PRKCSH and performed GSEA enrichment analysis on the differential genes to explore the biological function of PRKCSH in different cancers." (PMID 38245572, 2024). "Our findings revealed a strong correlation between PRKCSH expression and the immune cells in pan-cancer." (PMID 38245572, 2024). "Taken together, these findings signify a significant increase in PRKCSH expression in the majority of cancers, and this consistency is observed at both the gene and protein levels, laying the groundwork for further investigation." (PMID 38245572, 2024). "PRKCSH’s involvement in cancer is multifaceted, impacting cell growth, metastasis, and response to growth factors." (PMID 38571496, 2024). "Moving forward, we conducted an assessment of cancer-related functional states of PRKCSH at the single-cell sequencing level using the CancerSEA database." (PMID 38245572, 2024). "Further investigation is needed to understand PRKCSH’s intricate roles in cancer development, highlighting the importance of a comprehensive therapeutic approach." (PMID 38571496, 2024). "To confirm these effects, we investigated the effects of the ectopic overexpression of PRKCSH-WT or ΔG2B in the TNFSF-sensitive cancer cell line H460." (PMID 38200153, 2024). "The subsequent discussion explores the impact of PRKCSH on these programs, shedding light on its potential significance in cancer development." (PMID 38571496, 2024). "It is plausible that an increased level of PRKCSH may be a mechanism employed by cancer cells to suppress death pathways, explaining why the suppression of PRKCSH triggered cancer cell death." (PMID 38571496, 2024). "Finally, the Cmap analysis identified 24 small-molecule drugs with the potential therapeutic efficacy targeting PRKCSH in more than 4 cancer types." (PMID 38245572, 2024). "The activation of IRE1α by PRKCSH implies that inducing PRKCSH in cancer cells could influence their evasion of immunosurveillance." (PMID 38571496, 2024). "Gaining a comprehensive understanding of the intricacies surrounding PRKCSH may offer valuable insights into cellular glycosylation events, developmental processes, and potential implications in cancer." (PMID 38571496, 2024). "PRKCSH stands out as a potential therapeutic target to induce cancer cell death." (PMID 38571496, 2024). "This disparity, along with inconsistent correlations between PRKCSH (GluIIß) expression and GluIIα, suggests that PRKCSH may contribute to cancer development through mechanisms beyond its enzyme activity." (PMID 38571496, 2024). "Inhibiting PRKCSH could revitalize the immune response, enhancing NK cell-based cancer therapy by disrupting IGF1R stability and activation, thus overcoming TNFSF resistance." (PMID 38571496, 2024). "Moreover, elevated expression of PRKCSH was observed in cancer tissues from the liver, colon, gastric, breast, and lung." (PMID 38571496, 2024). "However, despite the essential role of PRKCSH in the glycosylation process, its immunological significance in human cancer remains poorly understood." (PMID 38245572, 2024).
cancer (continued). "Combining PRKCSH and lysosomal inhibitors may present a novel strategy for inducing extensive cancer cell death through apoptosis, but further clinical investigations are essential for validation." (PMID 38571496, 2024). "Based on this observation, we hypothesize that PRKCSH may protect cancer cells from being recognized and killed through inhibiting the proliferation of T cells." (PMID 38245572, 2024). "Additionally, PRKCSH’s regulation of IRE1α and cell adhesion molecules like PD-L1 underscores its potential as a target and marker for augmenting T cell responses against cancer." (PMID 38571496, 2024). "However, this inhibition was not reversed via ectopic expression of IGF1R in PRKCSH-deficient cancer cells." (PMID 38200153, 2024). "PRKCSH may play a cancer-promoting role through genetic alteration and DNA methylation." (PMID 38245572, 2024). "To investigate the relationship between the expression levels of PRKCSH and IGF1R in cancer patient tissues, we first analyzed IGF1R mRNA expression in various cancer tissues using the TCGA database." (PMID 38200153, 2024). "PRKCSH’s diverse functions, including regulation of IGF1R and IRE1α, implicate it as a therapeutic target and biomarker in cancer immunotherapy." (PMID 38571496, 2024). "PRKCSH expression was significantly correlated with both extrahepatic metastasis (chi-square test, P = 0.029) and TNM classification of malignant tumors (TNM) stage (chi-square test, P = 0.028)." (PMID 31320625, 2019). "PRKCSH expression was positively correlated with the expression of XBP1 target genes such as ER chaperones and ERAD components in various cancer tissues." (PMID 31320625, 2019). "Potential treatment options that target IRE1 signaling in cancer cells lacking PRKCSH are highlighted by this dysregulation." (PMID 41350724, 2025). "Our study found a negative correlation between PRKCSH expression and M1 macrophage infiltration in 6 cancer types, and a positive correlation with M2 macrophage infiltration in 12 types of tumors." (PMID 38245572, 2024). "More interestingly, a Glu-to-Gly recoding event in the PRKCSH gene has to our knowledge not been reported before in the context of cancer even though the gene itself is known as a potential cancer biomarker." (PMID 39062643, 2024). "Our data suggest that PRKCSH plays a critical role in TNFSF resistance and may be a potential target to improve the efficacy of NK cell-based cancer therapy." (PMID 38200153, 2024).
kidney disease (2 papers, 2024 to 2026). "Genetic testing with a 385-gene NGS-based kidney disease panel (the Renasight test) identified heterozygous truncating pathogenic variants in PKD1: c.3957_3994dup p.(Asp1332Glyfs*27)) (ClinVar ID VCV003376509.1) and PRKCSH: c.374_375del p.(Glu125fs)) (ClinVarID VCV001048653.34)." (PMID 41659942, 2026).
genetic disorders (1 paper, 2012). "Although the frequency of somatic second-hit mutations varies between different genes and genetic disorders, the difference in somatic mutations between cysts from PRKCSH patients and this SEC63 patient is remarkable." (PMID 23209713, 2012).
PRKCSH also shares sentences with these, for which no sentence is quoted: glioblastoma multiforme (3 papers); non-small cell lung carcinoma (3); diabetes (2); diffuse large B-cell lymphoma (2); esophageal carcinoma (2); liver cyst (2); lymphoid neoplasm (2); pancreatic adenocarcinoma (2); polycystic liver disease 1 (2); skin cutaneous melanoma (2); stomach adenocarcinoma (2); thymoma (2); acute lymphoblastic leukemia (1); bacterial infection (1); colon adenocarcinoma (1); colon cancer (1); congenital anomalies of the kidney and urinary tract (1); depression (1); early-onset Alzheimers disease (1); liver diseases (1); lung squamous cell carcinoma (1); medullary cystic kidney diseases (1); metabolic syndrome (1); nephronophthisis 1 (1); neuroblastoma (1); osteosarcoma (1); ovarian carcinoma (1); prostate carcinoma (1); renal cell carcinoma (1); retinoblastoma (1).